BDNF (brain derived neurotrophic factor)
Diseases named in the same sentence as BDNF in open-access papers (continued):
Sharing a sentence is not in itself a finding about the gene and the disease.
schizophrenia (continued). "The dominance of proBDNF in both maternal and fetal parts of the placenta in the hyperhomocysteinemia-induced schizophrenia animal model suggests that the dynamic balance between BDNF isoforms produced during the processing plays an important role in neuronal plasticity and cognitive development." (PMID 36438556, 2022). "Indeed, hypoactivity of NMDA and brain-derived neurotrophic factor (BDNF)/glial-cell derived neurotrophic factor (GDNF) receptors via gut microbiota alterations in central nervous system disorders including schizophrenia has also been reported." (PMID 35269766, 2022). "Indeed, a potential association between BDNF serum levels and schizophrenia (SCZ) and schizoaffective disorder (SAD) has been tested in diverse studies and a considerable amount of them found reduced BDNF levels in these disorders." (PMID 36552127, 2022). "Additionally, the hypofunction of calcineurin in schizophrenia animals, which displayed dysfunction in BDNF trafficking, had the potential to alter synaptic plasticity and memory behavior and result in profound disruptions of information processing." (PMID 36438556, 2022). "As such, reduced BDNF levels appeared to cut cross different psychiatric diagnostic categories and is not specific to psychosis or schizophrenia." (PMID 35447946, 2022). "Likewise, this study used the level of schizotypy as a proxy for the genetic-based liability to schizophrenia and the percentage of methylation of the BDNF promoter to represent environmental influence." (PMID 35853898, 2022). "Several kinds of literature have reported that proteolytic degradation of STEP occurs upon the synaptic NMDA receptor activation in Schizophrenia or the suppression of brain‐derived neurotrophic factor (BDNF) in neuropsychiatric disorders, as well as that does in long‐term potentiation and learning." (PMID 35838331, 2022). "Therefore, BDNF has a potential role in the treatment of neuropsychiatric disorders, including intellectual disability, schizophrenia, autism, and mood disorders." (PMID 36014820, 2022). "Another suggested pathomechanism in schizophrenia is changes in the BDNF expression." (PMID 35269761, 2022). "Our goal was to search for associations between BDNF, CRP, IL-6 and clinical symptoms, cognitive and personal performance in patients with paranoid schizophrenia to try to identify specific subtypes of patients and search for their potential therapeutic targets." (PMID 35873262, 2022). "We therefore set out to explore whether BDNF is associated with depressive symptoms in patients with first-episode and drug-naïve (FEDN) schizophrenia." (PMID 35757201, 2022). "Genes related to BDNF and glucose transport amongst others may partly explain the comorbidity between schizophrenia and cardiometabolic disorders." (PMID 35156041, 2022). "This may be considered a serious methodological limitation that prevents definitive conclusions about the role of the BDNF gene in schizophrenia in the Chinese Han population." (PMID 35368680, 2022). "BDNF has been proposed as a putative candidate biomarker for mood disorders and schizophrenia." (PMID 36672535, 2022). "The second-ranked gene, brain-derived neurotrophic factor (BDNF) has been implicated in schizophrenia but human studies have not clearly associated it with the disorder." (PMID 35073334, 2022). "By demonstrating the moderating role of schizotypy on the association between BDNF methylation and changes in the DMN-FPN network FC, this study provides pivotal neurobiological data substantiating the stress-vulnerability model of developing schizophrenia." (PMID 35853898, 2022). "Additionally, neuroprotective compounds including brain-derived neurotrophic factor (BDNF) are decreased in deficit schizophrenia." (PMID 36429996, 2022). "However, there has been limited attention to the role of epigenetic reprogramming of the BDNF gene in relation to the resting-state brain functional network in individuals with schizophrenia." (PMID 35853898, 2022).
schizophrenia (continued). "BDNF is important for dopamine sensitivity and the expression of dopamine D3 receptor subtype, the mRNA of which is decreased in patients with schizophrenia or bipolar disorder and increases following treatment; however, higher D3 levels correlated with negative schizophrenic symptoms." (PMID 35955546, 2022). "Some studies found significant positive association of BDNF with negative symptoms in schizophrenia and it has been suggested that the increased level of BDNF represents a compensatory response to the underlying neuropathology in the brain regions implicated." (PMID 35114967, 2022). "During the past 2 decades, many small- and large-scale studies have explored the association between BDNF gene polymorphisms (rs11030101, rs2030324, and rs6265) and schizophrenia, mainly with negative results." (PMID 35368680, 2022). "In a ketamine-induced schizophrenia-like deficit model, ketamine also reduced BDNF levels." (PMID 36172262, 2022). "Previous studies have shown that there is a significant association between BDNF gene polymorphisms and clinical negative symptoms of schizophrenia." (PMID 35368680, 2022). "Interactions between activated immune-inflammatory pathways and lowered BDNF may play a key role in schizophrenia." (PMID 36429996, 2022). "Serum BDNF levels were lower in patients with FEDN schizophrenia compared with healthy controls." (PMID 35757201, 2022). "Therefore, several studies have addressed the possible role of BDNF in neuropsychiatric disorders, including schizophrenia (SCZ) spectrum disorders." (PMID 36552127, 2022). "The result of this study suggests that neurofeedback training may strengthen the cognitive, clinical, and psychosocial rehabilitation of patients with schizophrenia, resulting in the increase in serum BDNF levels." (PMID 36672535, 2022). "Our haplotype analysis showed that the BDNF gene rs11030101/rs2030324/rs6265 AAC haplotype was more common in the schizophrenia group than in the control group, suggesting that this haplotype may be related to an increased susceptibility to schizophrenia." (PMID 35368680, 2022). "Thus, the purpose of this study was to explore the associations between the BDNF gene polymorphisms rs11030101, rs2030324, and rs6265 and the CREB gene polymorphisms rs6740584 and rs2551640 and schizophrenia." (PMID 35368680, 2022). "The distribution of genotype frequencies at each locus showed that the genotype at the BDNF locus, rs11030101, was predominantly AA in both the schizophrenia and control groups; the rs2030327 genotype was predominantly AG; and the rs6265 genotype was predominantly CT." (PMID 35368680, 2022). "Finally, the parallel changes in BDNF levels in plasma and CSF indicate that plasma BDNF levels reflect the brain changes in BDNF levels in schizophrenia." (PMID 34393855, 2021). "Still, most of the research regarding BDNF and cognitive symptoms in psychosis is carried out in relation to schizophrenia as a disease, so implementing studies devoid of the bias of traditional diagnostic categories represents a future challenge for this line of research." (PMID 34220575, 2021). "Schizophrenia is associated with low BDNF levels in the brain and blood, however, not much is known about BDNF’s role in the different symptoms of schizophrenia." (PMID 33888685, 2021). "Thus, the aim of this study was to investigate the role of BDNF in mouse behavioral endophenotypes of schizophrenia." (PMID 33888685, 2021). "The association of CRP with schizophrenia (Outlier-Corrected IVW β=-0.11; SE 0.03) was preserved in MR-PRESSO outlier-corrected IVW analysis, but the associations of trans variants for sIL-2Rα and BDNF with schizophrenia attenuated." (PMID 34280516, 2021). "BDNF is considered to play a major role in the pathogenesis of schizophrenia." (PMID 34434228, 2021). "Such gene–environment interactions support the hypothesis of a close relationship between tDCS-induced neural plasticity and BDNF, even in patients with schizophrenia." (PMID 34069556, 2021).
schizophrenia (continued). "BDNF levels are also low in the blood from schizophrenia patients." (PMID 34445065, 2021). "Here, we aimed to investigate whether tDCS modulates neural plasticity by measuring the acute effects of tDCS on peripheral mature BDNF levels in patients with schizophrenia." (PMID 34069556, 2021). "Another important interaction that may have influenced the results observed in patients with schizophrenia under antipsychotic medication is the close relationship between BDNF synthesis and central dopamine release." (PMID 34069556, 2021). "BDNF may be a useful biomarker in psychosis for early diagnosis, although the question about whether it can be helpful to predict conversion to schizophrenia in CHR subjects remains open." (PMID 34220575, 2021). "Our clinical study, consistent with previous postmortem brain study data, suggests that reduced BDNF in schizophrenia may partly be regulated by miR-195." (PMID 33558459, 2021). "In addition, a few studies have been conducted on the effect of chronic neuroinflammation on BDNF levels in patients with schizophrenia." (PMID 34763683, 2021). "Furthermore, male patients with schizophrenia had significantly lower BDNF and more unsatisfactory memory performance than their female counterparts, and in female patients, BDNF correlated significantly with immediate and delayed memory." (PMID 33882965, 2021). "Brain-derived neurotrophic factor (BDNF) is a neurotrophic factor that plays a role in the inflammatory pathway in the central nervous system, and it is considered a candidate gene for the pathogenesis of schizophrenia." (PMID 34831111, 2021). "Our hypothesis was that mature adult BDNF+/− mice express behavioral endophenotypes of schizophrenia that can be prevented by EE exposure." (PMID 33888685, 2021). "Schizophrenia patients generally have lower than normal levels of BDNF, which is thought to contribute to dysfunctional neural networks with altered neuroplasticity and synaptic formation/function, which makes the neural network more vulnerable to disturbances." (PMID 33333158, 2021). "Furthermore, altered BDNF/TrkB signalling has been observed in both rodent models and patients suffering from autism spectrum disorders and schizophrenia." (PMID 34360710, 2021). "Interestingly, many studies have found significant sex differences in BDNF levels in patients with schizophrenia." (PMID 34234699, 2021). "The results together imply that miR-195 regulates protein expression of BDNF at the clinical level, and suggest that combined miR-195 and BDNF assessments may represent a useful biomarker reflecting the miR-195 - BDNF pathway abnormalities in schizophrenia." (PMID 33558459, 2021). "Another factor is that BDNF polymorphism and its protein levels have been correlated to several other mental disorders, including schizophrenia and bipolar disorder, which would place BDNF as a biomarker for mental illness in general and explain some of the discrepancies." (PMID 34760029, 2021). "Moreover, BDNF protein levels were found to significantly mediate the effects of BDNF mRNA and miR-195 expressions on cognition in patients with schizophrenia." (PMID 33558459, 2021). "Hence, it is important to consider gender when measuring BDNF levels in patients with schizophrenia and metabolic indicators." (PMID 35047549, 2021). "Serum levels of cytokines, hsCRP, and BDNF in the schizophrenia group and the healthy control." (PMID 34393855, 2021). "Taking together evidence in vitro and post-mortem studies, BDNF may be involved in the pathophysiology of schizophrenia at all ages." (PMID 34239458, 2021). "Based on findings in animal studies and adult schizophrenia, it is speculated that in LLS patients, cognitive performance is at least partially associated with peripheral BDNF levels." (PMID 34239458, 2021).
schizophrenia (continued). "Recent advancements in psychiatric research has discovered that levels of brain-derived neurotrophic factor (BDNF) could correlate with neuroprotection in schizophrenia, with higher levels indicating better outcomes." (PMID 34449689, 2021). "The present study aimed to shed light on how coordination among the Kyn pathway, proinflammatory cytokines, and BDNF may influence the symptomatology in chronic hospitalized schizophrenia patients." (PMID 34393855, 2021). "Moreover, BDNF has been suggested to be a useful neurobiological biomarker of early-onset schizophrenia." (PMID 34299697, 2021). "Moreover, there were significant sex differences in the correlation between BDNF and cognition in patients with schizophrenia." (PMID 34234699, 2021). "Likewise, decreases in BDNF transcripts were detected in the cortico-hippocampal circuit of people with schizophrenia, highlighting the disturbance of synaptic plasticity-related signaling pathways BDNF-TrkB signaling." (PMID 35496352, 2021). "Indeed, multiple studies have indicated that BDNF plays a key role in the pathophysiology of schizophrenia." (PMID 34054433, 2021). "The BDNF levels were lower in patients with schizophrenia in both the serum and in the brain." (PMID 32351633, 2020). "Consequently, our findings would support a role for dysfunctional BDNF signaling as a failed repair mechanism in schizophrenia with consequences for neural connectivity." (PMID 32153434, 2020). "However, it deserves to be pointed out that our project was intended as a pilot study and is, to the best of our knowledge, the first to examine potential correlations between BDNF serum levels and white matter changes in schizophrenia." (PMID 32153434, 2020). "As the effects of AE on BDNF production are further studied in schizophrenia, examination of how the microbiome influences this pathway may be illuminating." (PMID 32719625, 2020). "However, further studies are necessary to elucidate the role of BDNF in oligodendrocytes in the therapeutic effect of quetiapine in the MK-801–induced schizophrenia animal model." (PMID 32973585, 2020). "The deficits in SST and SST+ neurons observed in subjects with schizophrenia and animal models of schizophrenia may be a downstream consequence of impaired BDNF signaling." (PMID 33192369, 2020). "BDNF is extensively studied to be an important factor of schizophrenia pathology or pathogenesis." (PMID 32793005, 2020). "Consequently, little is known about a relationship between BDNF and white matter microstructure in actual schizophrenia patients." (PMID 32153434, 2020). "The decreased peripheral concentration of BDNF is widely observed in patients with schizophrenia." (PMID 32793005, 2020). "Hence, seeing increased dendritic growth and synaptic plasticity as a result of upregulated BDNF in schizophrenia patients and therefore resulting in a positive correlation with FA seems unlikely." (PMID 32153434, 2020). "In this article, we review the existing evidence implicating dysbiosis in schizophrenia and discuss how the presumed dysbiosis could fit within known hypotheses of its pathogenesis, focusing on inflammation, tryptophan metabolites, and BDNF levels." (PMID 32226399, 2020). "Again, none of these studies is directly related to the microbiome in schizophrenia, and more convincing data could be obtained from studies analyzing the effects of FMT from schizophrenia patients on BDNF expression." (PMID 32226399, 2020). "Studies in chronic schizophrenia patients have shown decreased levels of BDNF." (PMID 32752263, 2020). "BDNF is involved in manifold systemic metabolic processes of the body, and therefore a relatively high concentration of 32.69 ± 8.33 ng/mL BDNF is present in human blood serum and down-regulated during several diseases, e.g., systemic lupus erythematosus and schizophrenia." (PMID 32927875, 2020).
schizophrenia (continued). "Therefore, RSV treatment ameliorates the depressed CREB/BDNF pathway in the neonatal rat schizophrenia model through enhancing SIRT1 expression." (PMID 32793005, 2020). "BDNF may act on oligodendrocyte expressed tropomyosin-related kinase (Trk) B to potentiate and enhance myelination, and is relevant for schizophrenia-related phenotypes." (PMID 32973585, 2020). "The BDNF dysfunction in the schizophrenia has been soundly documented." (PMID 32351633, 2020). "In this pilot study, we wanted to explore whether there was an association between micro- and mesostructural grey matter/fiber tract changes and BDNF serum levels in schizophrenia." (PMID 32153434, 2020). "A large amount of evidence showed BDNF may be related to the pathophysiology of schizophrenia because of its role in the development, regeneration, survival and maintenance of brain neurons." (PMID 31420036, 2019). "N−3 polyunsaturated fatty acids (n−3 PUFA) influence multiple biochemical mechanisms postulated in the pathogenesis of schizophrenia that may influence BDNF synthesis." (PMID 31098654, 2019). "The inconsistency of previous studies on the association of BDNF and GDNF with schizophrenia may be related to the confounding effects of the severity of symptoms, age, gender, sample population, different stages of illness and medication history." (PMID 31420036, 2019). "For example, BDNF is associated with CRF, cognition, and schizophrenia, and a mediating role between CRF and cognition may be obscured by disorder-specific effects in schizophrenia." (PMID 31708824, 2019). "A main factor considered to be involved in the pathogenesis of schizophrenia is BDNF." (PMID 31614739, 2019). "Many evidences suggest that BDNF is involved in the pathophysiological process of schizophrenia." (PMID 31420036, 2019). "Moreover, Kimhy and colleagues found that aerobic exercise improved levels of BDNF in a sample of individuals with schizophrenia, as compared to controls." (PMID 31708824, 2019). "BDNF is reduced in participants with schizophrenia, and increasing protein levels may have beneficial clinical outcomes." (PMID 31185023, 2019). "Moreover, a significant increase in BDNF levels in prefrontal cortex and cerebrospinal fluid samples of postmortem schizophrenia patients was reported." (PMID 32116676, 2019). "Reduced BDNF level in PFC has been reported in the patients with schizophrenia." (PMID 31261897, 2019). "Of the total of 34 proteins screened, 5 proteins associated with psychoneuroimmune pathways in schizophrenia were analyzed, which could be potential new analytes: drebrin, GMF-β, BDNF, RAB3GAP1, and attractin." (PMID 31849731, 2019). "Serum BDNF levels and demographic data of patients with schizophrenia and healthy controls." (PMID 30794585, 2019). "Additionally, nicotine alters cholinergic signaling, increases global BDNF levels, and is highly used in persons with schizophrenia." (PMID 31185023, 2019). "Serum BDNF levels have been related to hippocampal volumes in first-episode schizophrenia patients." (PMID 31098654, 2019). "Increase in serum BDNF and plasma oxytocin levels in patients with schizophrenia." (PMID 31651843, 2019). "Serum BDNF may be an unsuitable biomarker for DS, despite a significant decrease in schizophrenia patients." (PMID 31420036, 2019). "In summary, aging in schizophrenia patients could lessen the influence of the disease, and BDNF changes may decelerate as schizophrenia patients' age." (PMID 29896133, 2018). "Dysfunction of BDNF signaling leads to deficits in neuronal growth and synaptic transmission, leading to disorganized brain function, which contributes to the development of schizophrenia." (PMID 30214393, 2018). "This posited estrogen-BDNF interaction could play a key role in sex differences in clinical aspects of schizophrenia." (PMID 29867348, 2018). "Thus, several studies indicate an increase of the BDNF levels and gene expression in patients with schizophrenia." (PMID 30327610, 2018).